CCND1 (cyclin D1)
Diseases named in the same sentence as CCND1 in open-access papers (continued):
Sharing a sentence is not in itself a finding about the gene and the disease.
Cerebral ischemia (5 papers, 2018 to 2024). Restriction of arterial blood supply to the brain associated with insufficient oxygenation to support the metabolic requirements of the tissue. "The accumulation of cyclin D1 caused by cerebral ischemia promotes programmed cell death by activating CDKs; Mor downregulated cyclin D1 and CDK6 to protect the brain." (PMID 39301568, 2024). "Significantly, many studies reported that cyclin D1 levels are increased in models of cerebral ischemia." (PMID 36159397, 2022). "For example, enhanced expression of cyclin D1 in the hippocampus induced by transient global brain ischemia in rats is localized to apoptotic granule cells located in the dentate gyrus, but not CA1 cells." (PMID 34439951, 2021). "Cyclin D1 has been studied in many in vivo (animal) models of neuronal cell death and/or degeneration following brain diseases such as brain ischemia." (PMID 34439951, 2021). "In animal models of brain and spinal cord ischemia, cyclin D1 and cdk4 expressions are increased in neurons and/or glial cells after focal brain ischemia in mice and rats, global brain ischemia in rats, and spinal cord ischemia in rabbits." (PMID 34439951, 2021). "Inadequate activation of cell cycle proteins including cyclin D1 and cdk4 is involved in neuronal cell death induced by diverse pathological stresses, including transient global brain ischemia." (PMID 34439951, 2021). "In contrast, other researches demonstrate that cyclin D1 mRNA and/or protein are upregulated in astrocytes and microglia located in the hippocampal CA1, rather than in pyramidal neurons, in rat models of transient forebrain or transient global brain ischemia." (PMID 34439951, 2021). "We previously showed that exogenous overexpression of miR-424 in the brain protects against permanent focal cerebral ischemia injury via suppression of microglia-mediated inflammatory response by reducing the expression of cell cycle proteins CDK6, cyclin D1, CDC25A." (PMID 29675290, 2018).
colorectal adenocarcinoma (5 papers, 2014 to 2025). The most common type of colorectal carcinoma. "Consistent with our findings, miR-421 was previously highlighted as a tumor-suppressive miRNA that restrains the malignant characteristics of CRC cells, while KDM2A is known to serve as a cyclin D1-associated mediator facilitating cell proliferation and colony formation in colorectal adenocarcinoma." (PMID 35508523, 2022). "The expression of cyclin B1, cyclin D1 and cyclin A was decreased by resveratrol in SW480 human colorectal adenocarcinoma cells." (PMID 27007366, 2016).
cyst (5 papers, 2022 to 2025). A sac-like closed membranous structure that may be empty or contain fluid or amorphous material. "Our snRNA-seq results showed that PCNA, Cyclin D1 and Caspase3 levels were increased in cyst cells compared to all other kidney cells." (PMID 37583898, 2023). "Here, we aimed to recognize the oncogenic mutations responsible for the stepwise development of LGSOC using immortalized HOVs-cyst-1 cells, developed from ovarian serous cystadenoma cells, and immortalized via cyclin D1, CDK4R24C, and hTERT gene transfection." (PMID 35326657, 2022). "PCNA, Cyclin D1 and Caspase3 were upregulated in cyst cells compared to all other kidney cells." (PMID 37583898, 2023). "The experimental HOVs-cyst-1 cells were first established from serous cystadenoma epithelial cells of the ovary without any existing carcinomas and then immortalized by overexpression of cyclin D1, CDK4, and hTERT." (PMID 35326657, 2022). "Hyperandrogenism, coupled with impaired apoptosis and dysregulated cell cycle genes (e.g., CCND1, CDK6), prevents proper ovarian follicular selection and dominance, leading to cyst formation." (PMID 40725447, 2025). "By modulating the Cyclin D1/CDK4/Rb axis and p19 regulation, ANKHD1 inhibition could potentially slow cyst growth and disease progression." (PMID 40457431, 2025).
ductal carcinoma in situ (5 papers, 2003 to 2021). "A separate investigation determined the cyclin D1 positivity in proliferative disease without atypia, atypical ductal hyperplasia, low-grade ductal carcinoma in situ (DCIS), high-grade DCIS, and invasive carcinoma." (PMID 33920506, 2021).
endometrioid carcinoma (5 papers, 2013 to 2025). "Moreover, CCND1 overexpression in endometrial lesions is substantially linked to endometrioid carcinoma, clear cell carcinoma, and atypical complex hyperplasia." (PMID 39188436, 2024). "In Type I endometrioid adenocarcinoma, mutations in PTEN, K-Ras, and β-Catenin lead to the activation of key pathways such as PI3K-Akt, MAPK, and Wnt, which promote CCND1 overexpression through β-Catenin-mediated TCF/LEF transcription and activation of c-Myc." (PMID 39940659, 2025). "In endometrioid carcinoma, CCND1 expression ranged from low to strong, as illustrated in and, respectively, demonstrating variability in expression within this histological subtype." (PMID 39940659, 2025). "They found elevated expression of the MMP-7, CCND1 (Cyclin D1), CX43 (Connexin 43), ITF2 and also PPARβ/δ genes in ovarian endometrioid adenocarcinomas with deregulated β-catenin." (PMID 32375405, 2020).
heart failure (5 papers, 2018 to 2026). Inability of the heart to pump blood at an adequate rate to meet tissue metabolic requirements. "Dysregulation of the CCND1 signaling pathway was responsible for the pathological process of ventricular remodeling, which subsequently turned into severe heart failure, conceiving high risk of embolic stroke." (PMID 30627556, 2018). "Notably, heart failure markers such as Cyclin D1 and atrial natriuretic peptide (NPPA) were upregulated in the hearts of obese mice and normalized in the HF + LP group." (PMID 41549510, 2026).
hypopharyngeal carcinoma (5 papers, 2004 to 2024). Carcinoma, predominantly squamous cell, arising from the epithelial cells of the hypopharynx. "It was reported that the strength and pattern of EpCAM expression are both positively correlated with the proliferation marker Ki-67, high expression and nuclear localisation of cyclin D1, and Rb phosphorylation in hypopharynx carcinoma in vivo, further validating its role in tumorigenesis." (PMID 30419852, 2018). "A significant association of point mutations in CCND1 and CDKN2A, as well as chromosomal instability based on copy number variation, was associated with progression-free survival in oropharyngeal and hypopharyngeal carcinoma independent of HPV status according to mutation analyses of 556 genes." (PMID 33801877, 2021).
intestinal polyp (5 papers, 2012 to 2023). Discrete abnormal tissue masses that protrude into the lumen of the intestine. "Next, we confirmed that heat-killed EC-12 suppressed the transcriptional activity of the T-cell factor/lymphoid enhancer factor, a transcriptional factor involved in cyclin D1 mRNA expression in intestinal polyps." (PMID 28406434, 2017).
kidney tumor (5 papers, 2016 to 2024). "CCND1 dysregulation was associated with cellular proliferation and tumor growth of kidney tumor." (PMID 27634882, 2016). "In our experiment, upregulation of cyclin D1 was observed not only in renal tumors of ChREBP-KO mice but also in kidney tissue of diabetic WT mice." (PMID 39518998, 2024). "Recently, a number of studies have suggested that immunohistochemical stain Cyclin D1 is useful in distinguishing CCSK from some pediatric renal neoplasms." (PMID 30736802, 2019). "The aim of the present study was to determine the usefulness of Cyclin D1 in distinguishing CCSK from other pediatric renal neoplasms and to see whether our findings match those in other recently published studies." (PMID 30736802, 2019). "The mRNA expression of CCND1 and PECAM1/CD31 were compared between kidney tumor samples and adjacent normal tissues respectively based on RNA-sequence data from TCGA database." (PMID 31850854, 2019). "In this study, we aim to determine the usefulness of Cyclin D1 in differentiating between CCSK and other pediatric renal neoplasms and to compare our results with those of recently published studies." (PMID 30736802, 2019). "Using immunohistochemistry, we observed strong nuclear positivity for cyclin D1 in renal tumors of non-diabetic ChREBP-KO mice." (PMID 39518998, 2024).
laryngeal tumor (5 papers, 2019 to 2024). "A major regulator of the G1/S transition in the cell cycle, CCND1, which encodes cyclin D1, is often overexpressed in laryngeal tumors, which leads to unchecked cell proliferation." (PMID 39452555, 2024). "In advanced larynx cancer, overexpression of Cyclin D1 is a known predictive marker of both overall and disease-free survival." (PMID 35626215, 2022). "Postoperative IHC results of the laryngeal tumor were as follows: CD20 (+), CD79a (+), CD3 (−), CD10 (−), Bcl-2 (+), CD5 (−), Cyclin D1 (−), and CD23 (−)." (PMID 39290501, 2024). "In brief, EHD inhibited laryngeal tumour growth in a xenograft mouse model of PCBS syndrome and regulated the STAT3/cyclin D1 signalling pathway." (PMID 32382281, 2020).
liver disease (5 papers, 2016 to 2022). "Furthermore, during the early phase of liver disease HO-1 function may alternatively affect regenerative proliferation in Mdr2−/− mice through interfering with Cyclin D1 expression up to 5 months after termination of treatment." (PMID 30389969, 2018).
lymphoid tumors (5 papers, 2010 to 2025). "In addition, TNBC tumors often have CCND1 amplifications, and CCND1 overexpression reduces global transcription activity and increases RNA polymerase II pausing, thereby sensitizing lymphoid tumor cells to inhibition of the TM via CDK7 or CDK9." (PMID 36139513, 2022). "SOX-11 mRNA and nuclear protein expression are seen in nearly all cyclin D1 positive and negative MCLs, but not in other mature lymphoid neoplasms or in normal lymphocytes." (PMID 39258061, 2024). "Cyclin D1 is overexpressed in a broad range of solid malignancies, expressed in lymphoid tumors such as MM and MCL and not in their normal counterparts." (PMID 20459741, 2010). "Markers for lymphoid neoplasms (CD3, CD5, and CD20), cyclin D1, and BCL2 were negative, and EBER in situ hybridization was also negative, effectively excluding lymphoid and viral-driven differentials." (PMID 40951125, 2025).
mucosal (5 papers, 2011 to 2021). "We also found that the AA genotype of CCND1 rs9344 was associated with a decreased risk of grade 3–4 oral mucositis among patients < 51 years old." (PMID 28445979, 2017). "It remained unclear if the lower level of PCNA and cyclin-D1 in CS treated groups is caused by a direct suppression effect or due to the mild mucositis resulting in less expression of the genes relevant to crypts regeneration." (PMID 24367389, 2013). "Interestingly, elevations of PCNA and cyclin-D1 were observed in all 5-Fu treated groups, suggesting a healing process from the experimental mucositis." (PMID 24367389, 2013).
neuroendocrine tumors (5 papers, 2017 to 2025). "Inhibition of CBP/β-catenin signaling also led to decreased cyclin D1 expression in soft tissue sarcomas and neuroendocrine tumors." (PMID 41227355, 2025). "Expression of c-Myc and cyclin D1 was also downregulated in neuroendocrine tumor cell lines treated with LGK974." (PMID 33923996, 2021).
oligodendroglioma (5 papers, 2018 to 2021). A well-differentiated (WHO grade II), diffusely infiltrating neuroglial tumor, typically located in the cerebral hemispheres. "The expression of CCND1 in microglia cells contributes to the differential diagnosis of oligodendrogliomas." (PMID 33193404, 2020).
osteoporosis (5 papers, 2020 to 2022). A condition of reduced bone mass, with decreased cortical thickness and a decrease in the number and size of the trabeculae of cancellous bone (but normal chemical composition), resulting in increased fracture incidence. "MiR-23b-3p functions as a positive factor for the progression of osteoporosis via targeting Ccnd1 in MC3T3-E1 cells." (PMID 35473505, 2022). "To conclude, findings in this study suggested that Arctiin could regulate MC3T3-E1 osteoblast differentiation via up-regulating Ccnd1, supporting that Arctiin might be a therapeutic target for osteoporosis." (PMID 35473505, 2022). "It is interesting to note that miR‐34s serve as an inhibitor in osteoblast proliferation by decreasing levels of Cyclin D1, CDk4, and CDK6 and a suppressor in osteoblast differentiation by decreasing SATB2 to facilitate the progression of osteoporosis." (PMID 33434305, 2021).
primary effusion lymphoma (5 papers, 2020 to 2024). A large B-cell lymphoma located in the body cavities, characterized by pleural, peritoneal, and pericardial fluid lymphomatous effusions and that is always associated with human herpes virus-8 (HHV-8). "It has been indicated that quercetin suppresses STAT3 and PI3K/AKT/mTOR pathways in primary effusion lymphoma (PEL) cells leading to downregulate the prosurvival cellular proteins expression, including cMyc, cyclin D1, and c-FLIP." (PMID 32175075, 2020). "Different subtypes can be identified via an additional IHC panel consisting of Cyclin D1, kappa/lambda, CD30, CD138, EBER-ISH, ALK, and HHV8 (primary effusion lymphoma)." (PMID 33216822, 2020). "Additionally, quercetin inhibits PI3K/AKT/mTOR and STAT3 pathways specifically in primary effusion lymphoma (PEL) cells, leading to downregulation in the expression of the pro-survival cellular proteins such as c-FLIP, cyclin D1, and c-Myc." (PMID 35956766, 2022).
pulmonary hypertension (5 papers, 2011 to 2022). Increased pressure within the pulmonary circulation due to lung or heart disorder. "For instance, hsa_Circ_0016070 promotes the proliferation of pulmonary artery smooth muscle cells (PASMCs) and participates in vascular remodeling in pulmonary hypertension (PAH) via the miR-942/CCND1 axis." (PMID 35690768, 2022). "Genes involved in cell proliferation, the cyclin family of genes and BCl2, were upregulated in the right ventricle of rats with pulmonary hypertension induced by monocrotaline, and the same was the case for cyclin D1 and D2 as well as BCl2 in the present study." (PMID 21246034, 2011).
rectum adenocarcinoma (5 papers, 2017 to 2023). An adenocarcinoma arising from the rectum. "We found significant correlations between expression levels of STAT2 and those of STAT3 and cyclin D1, respectively, in tumor samples from colon and rectum adenocarcinoma." (PMID 38001683, 2023). "(F) Data for LAST and CCND1 expression levels in READ (rectum adenocarcinoma) tumor and normal tissues were downloaded from the TCGA dataset." (PMID 29199958, 2017). "In a further analysis, we determined the alteration frequencies of c-Met/GSK3β/MYC/CCND1 gene signatures in CRC, COAD, and rectal adenocarcinoma (READ) tissues." (PMID 36672275, 2023).
renal fibrosis (5 papers, 2017 to 2025). A final common manifestation of a wide variety of chronic kidney diseases characterized by glomerulosclerosis and tubulointerstitial fibrosis. "Proteomic screening and validation studies demonstrated that DcR2 mediated tubular cell cycle arrest through the GSK3b/cyclin D1 signalling axis, contributing to renal fibrosis following AKI." (PMID 40845179, 2025).
acute promyelocytic leukemia (4 papers, 2015 to 2024). An aggressive form of acute myeloid leukemia (AML), characterized by arrest of leukocyte differentiation at the promyelocyte stage, due to a specific chromosomal translocation t(15;17) in myeloid cells. "Upregulation of UBE2D3 in acute promyelocytic leukemia cells leads to the ubiquitination of cyclin D1 and its degradation in the proteasome." (PMID 25789002, 2015). "Interestingly, UBE2D3 was found upregulated in ATRA-treated NB4 acute promyelocytic leukemia cells, leading to UBE2D3-mediated degradation of cyclin D1 and cell cycle arrest." (PMID 37059365, 2023).
adenoid cystic carcinoma (4 papers, 2009 to 2020). A malignant tumor arising from the epithelial cells. "In addition, AP2M1 is positively associated with cyclin D1 in adenoid cystic carcinoma (AdCC) and mucoepidermoid carcinoma (MEC), indicating that AP2M1 are involved in the proliferation of AdCC and MEC to cause tumor growth." (PMID 32943990, 2020). "Other major proliferation or anti-apoptotic markers, such as Ki-67, bcl-2, and cyclin D1, were frequently expressed in adenoid cystic carcinoma, but they had less of an impact on the discrimination of histological grade of adenoid cystic carcinoma." (PMID 19250538, 2009).
angiosarcoma (4 papers, 2016 to 2024). A malignant tumor arising from the endothelial cells of the blood vessels. "• In rat and human angiosarcoma, miR-23 target genes (Ccnd1, Adam19, Plau, and Wsb1) that increase invasiveness and metastasis were enriched." (PMID 38826780, 2024). "Expression of cyclin D1 (CCND1), a cell proliferation marker, VEGFA and VEGF165 (a splice variant of VEGFA), potent inducers of angiogenesis, was significantly higher in angiosarcoma cells than in normal endothelial cells and HAMON cells showed higher expression than ISO-HAS-B." (PMID 35256687, 2022).
Barrett esophagus (4 papers, 2006 to 2019). Esophageal lesion lined with columnar metaplastic epithelium which is flat or villiform.
basal cell carcinoma (4 papers, 2011 to 2020). A carcinoma involving the basal cells. "Activation of the HH pathway increases cyclin D1 and B1 expression leading to an increase in proliferation in basal cell carcinoma." (PMID 31820036, 2020). "The anal cancers had increased expression and nuclear localization of activated β-catenin and cyclin D1 consistent with the earlier observation that targeted expression of active β-catenin in the skin of Vdr−/− mice induces basal cell carcinoma." (PMID 27768599, 2016). "Our results confirm the hypothesis proposed by Staibano et al7, that analysis of cyclin D1 expression and DNA ploidy may help identifying basal cell carcinoma of head and neck with aggressive phenotype and poor outcome." (PMID 21537090, 2011).
colon adenoma (4 papers, 2005 to 2025). An adenoma that arises from the colon. "Similar results were demonstrated by a study from 2011, where it was shown that ibuprofen induced both IκBα degradation and nuclear localization of NFκB in human colon adenoma cells, however the activation of NFκB target genes (Bcl-2, survivin, cyclin D1) was suppressed." (PMID 40408503, 2025). "In addition, in flat and exophytic human colon adenomas, cyclin D2 was overexpressed in considerably larger proportions than cyclin D1." (PMID 16012517, 2005).
colorectal adenoma (4 papers, 2006 to 2021). An adenoma that arises from the colon or rectum. "However, a validation study in colorectal adenomas has evaluated the validity of a TMA constructed from colorectal adenoma tissue for selected immunohistochemical expression including Ki-67 and cyclin D1." (PMID 34762658, 2021).
depression (4 papers, 2012 to 2023). "Rats with subclinical hypothyroidism-associated depression exhibited increased levels of GSK-3β and phosphorylated β-catenin, while c-myc and cyclin D1 were decreased." (PMID 30200269, 2018). "Based on our findings, the abnormal expression of β-catenin and its associated dysfunction of cyclin D1 and c-myc may play a key role in SCH-associated depression." (PMID 27252679, 2016).